FBXO41 (F-box protein 41)
Description:
Substrate-recognition component of the SCF (SKP1-CUL1-F-box protein)-type E3 ubiquitin ligase complex.
Synonyms: FBX41; KIAA1940
Tractability: Antibody: the Human Protein Atlas places it where antibodies can reach. PROTAC: ubiquitination databases record sites on it; its protein half-life has been measured.
Gene: Protein-coding gene on chromosome 2 (73,254,682 to 73,284,478, reverse strand). Ensembl gene ENSG00000163013.
Subcellular location (Human Protein Atlas): Cytosol; Nucleoplasm; Plasma membrane
Pathways (Reactome):
Immune System: Antigen processing: Ubiquitination & Proteasome degradation
Metabolism of proteins: Neddylation
Gene Ontology:
Biological process: SCF-dependent proteasomal ubiquitin-dependent protein catabolic process
Cellular component: cytosol; SCF ubiquitin ligase complex; centrosome; cytoplasm
Genetic constraint (gnomAD): Loss-of-function variants: 33 observed, 56.39 expected, observed/expected ratio (o/e) 0.59, 90% interval 0.44 to 0.78. The synonymous counts are far from expectation, so gnomAD's model fits this gene poorly and the ratio says little. Missense variants: 1,107 observed, 1,014.2 expected, observed/expected ratio (o/e) 1.09, 90% interval 1.04 to 1.15. Synonymous variants: 576 observed, 448.46 expected, observed/expected ratio (o/e) 1.28, 90% interval 1.2 to 1.38.
Homologues: Orthologues: macaque FBXO41 (99% identical), chimpanzee FBXO41 (99% identical), dog FBXO41 (98% identical), pig FBXO41 (97% identical), guinea pig FBXO41 (97% identical), rat Fbxo41 (97% identical), mouse Fbxo41 (97% identical), tropical clawed frog fbxo41 (67% identical), zebrafish fbxo41 (64% identical). Paralogues in human: ZNF365 (14% identical).
Diseases named in the same sentence as FBXO41 in open-access papers:
FBXO41 is named in the same sentence as 4 diseases in open-access papers, as found by Europe PMC text mining. Sharing a sentence is not in itself a finding about the gene and the disease. The quoted sentences say what the papers report.
Ataxia (1 paper, 2022). Ataxia refers to impaired coordination of voluntary muscle movement. "Fbxo41 mutations have been linked to neurological abnormalities both in humans and in mice: Fbxo41 KO mice show neuronal migration defects in the cerebellum, signs of neurodegeneration, and severe motor deficits, resembling ataxia." (PMID 35372812, 2022).
epileptic encephalopathies (1 paper, 2022). "In humans, a de novo heterozygous nonsense mutation in FBXO41 was detected in exome-sequencing data of 356 patients with epileptic encephalopathies." (PMID 35372812, 2022). "FBXO41 is a neuron-specific E3 ligase subunit implicated in epileptic encephalopathies." (PMID 35372812, 2022).
microcephaly (1 paper, 2022). A congenital or acquired developmental disorder in which the circumference of the head is smaller than normal for the person's age and sex. "FBXO41 shares molecular and phenotypic features with microcephaly genes: it accumulates at centrosomes, and its absence results in a decrease of RGL cell numbers, without affecting the number of mature neurons." (PMID 35372812, 2022).
FBXO41 also shares sentences with these, for which no sentence is quoted: cancer (1 paper).